SRMS (src-related kinase lacking C-terminal regulatory tyrosine and N-terminal myristylation sites)
Description:
Non-receptor tyrosine-protein kinase which phosphorylates DOK1 on tyrosine residues. Also phosphorylates KHDRBS1/SAM68 and VIM on tyrosine residues. Phosphorylation of KHDRBS1 is EGF-dependent. Phosphorylates OTUB1, promoting deubiquitination of RPTOR.
Synonyms: C20orf148; SRM; dJ697K14.1; PTK70
Tractability: Small molecule: an approved drug acts on it; a high-quality ligand is known; it belongs to a druggable protein family. Antibody: its Gene Ontology location is reachable by antibodies, with medium confidence. PROTAC: a small molecule that binds it is known.
Target class: TK protein kinase group; Tyrosine protein kinase Src family; Tyrosine protein kinase Srm; Enzyme; Kinase; Protein Kinase
Gene: Protein-coding gene on chromosome 20 (63,538,489 to 63,547,749, reverse strand). Ensembl gene ENSG00000125508.
Subcellular location: Cytoplasm
Subcellular location (Human Protein Atlas): Intermediate filaments; Actin filaments; Cytosol
Pathways (Reactome):
Signal Transduction: PTK6 Down-Regulation
Gene Ontology:
Molecular function: protein binding; protein tyrosine kinase activity; non-membrane spanning protein tyrosine kinase activity; signaling receptor binding; ATP binding; protein kinase activity
Biological process: peptidyl-tyrosine autophosphorylation; peptidyl-tyrosine phosphorylation; positive regulation of TORC1 signaling; cell differentiation; cell surface receptor protein tyrosine kinase signaling pathway; negative regulation of signal transduction
Cellular component: cytoplasm; cytosol; plasma membrane
Genetic constraint (gnomAD): Loss-of-function variants: 42 observed, 37.59 expected, observed/expected ratio (o/e) 1.12, 90% interval 0.87 to 1.45. The upper end of that interval is the gene's LOEUF score, 1.45, which puts it in group 5 of 6, group 1 being the genes least tolerant of losing a copy. Missense variants: 703 observed, 614.74 expected, observed/expected ratio (o/e) 1.14, 90% interval 1.07 to 1.22. Synonymous variants: 316 observed, 274.59 expected, observed/expected ratio (o/e) 1.15, 90% interval 1.05 to 1.26.
Homologues: Orthologues: macaque SRMS (95% identical), chimpanzee SRMS (91% identical), guinea pig SRMS (79% identical), rat Srms (79% identical), mouse Srms (78% identical), pig SRMS (77% identical), dog SRMS (74% identical), zebrafish srms (45% identical). Paralogues in human: PTK6 (42% identical), FGR (41% identical), FYN (41% identical), SRC (41% identical), BLK (41% identical), FRK (41% identical), LCK (40% identical), YES1 (40% identical), HCK (39% identical), LYN (38% identical), ABL2 (36% identical), ABL1 (36% identical), and 20 more.
Diseases named in the same sentence as SRMS in open-access papers:
SRMS is named in the same sentence as 20 diseases in open-access papers, as found by Europe PMC text mining. Sharing a sentence is not in itself a finding about the gene and the disease. The quoted sentences say what the papers report.
breast carcinoma (4 papers, 2020 to 2021). "Numerous copy number gains and missense mutations involving SRMS were identified in breast cancer and other cancers, but the functional effects are not presently characterized." (PMID 32545875, 2020). "We analyzed data from the METABRIC cohort of 2,173 breast cancer patients and found that approximately 7% (145 patients) exhibited amplification of the SRMS locus within their tumors." (PMID 34077419, 2021). "In breast cancer, the levels of SRMS expression have been found to be correlated with the grade and severity of the tumor." (PMID 34510798, 2021). "To address this, we measured the growth of human breast cancer cells after depletion of SRMS alone versus co-depletion of SRMS and core autophagy genes." (PMID 34077419, 2021). "SRMS, like Brk, is highly expressed in most breast carcinoma cells compared to normal mammary cell lines and tissues." (PMID 32545875, 2020). "Indeed, endogenous SRMS was found to localize to distinct punctate cytoplasmic structures in three breast cancer cell lines (MDA-MB-231, AU565, and SKBR3) and in the cervical cancer cell line HeLa." (PMID 32545875, 2020). "Dok1 and SRMS were shown to be co-expressed in several breast cancer cell lines, including HBL100." (PMID 32545875, 2020). "Interestingly, SKBR3 breast cancer cells have high expression of SRMS protein levels." (PMID 34077419, 2021). "SRMS belongs to a family of nonreceptor tyrosine kinases that have been involved in a number of cancers, including fibrosarcoma, eosinophilic variant of chromophobe renal cell carcinoma, and breast cancer, but its function in gliomagenesis remains unknown." (PMID 33169458, 2021). "Taken together, ibrutinib has potential as an anticancer drug in the setting of breast cancer and may act through direct inhibition of multiple kinases including BTK-C, Her2, SRMS, and others depending on the specific context." (PMID 34077419, 2021). "Interestingly, SRMS is overexpressed in breast cancer cells relative to nontumorigenic breast epithelial cells." (PMID 34077419, 2021).
colorectal cancer (2 papers, 2021 to 2025). A primary or metastatic malignant neoplasm that affects the colon or rectum. "SRMS overexpression in colorectal cancer is associated with a poor prognosis." (PMID 40001606, 2025). "However, the role of SRMS in colorectal cancer (CRC) has not been well established." (PMID 34781983, 2021).
glioma (2 papers, 2021 to 2023). A benign or malignant brain and spinal cord tumor that arises from glial cells (astrocytes, oligodendrocytes, ependymal cells). "Changes in the activity of an enhancer on 20q13.33 led to abnormal expression of multiple genes associated with glioma risk (e.g., RTEL1, RTEL1-TNFRSF6B, SRMS and GMEB2)." (PMID 37349788, 2023).
colon adenocarcinoma (1 paper, 2021). "Data in the Oncomine database, including TCGA colorectal and Kurasgina colorectal, showed that CNVs of SRMS were significantly elevated in colon adenocarcinoma (COAD) tissues than in paired normal tissues (p < 0.01)." (PMID 34781983, 2021). "In colon adenocarcinoma (COAD), the expression levels of SRMS are significantly correlated with pathological stages and nodal metastasis status." (PMID 34781983, 2021).
endometrial cancer (1 paper, 2014). Primary or metastatic malignant neoplasm involving the endometrium (mucous membrane that lines the endometrial cavity). "For example, a chromosome 20q cluster comprising four genes (PTK6, SRMS, RTEL1, and PRPF6) were all amplified in uterine/endometrial cancers and lung adenocarcinomas." (PMID 24874471, 2014).
epilepsy (1 paper, 2021). A brain disorder characterized by episodes of abnormally increased neuronal discharge resulting in transient episodes of sensory or motor neurological dysfunction, or psychic dysfunction. "Interestingly, we observed that when compared to the normal controls, the expression of some identified genes was only significantly altered either in Epilepsy (EGLN1, ELAVL4, and NFE2l2) or Hemorrhage (USP22, EYA1, SIX1, OAS3, SRMS) groups." (PMID 34588521, 2021).
lymph node metastasis (1 paper, 2021). "In addition, high expression levels of SRMS have been associated with advanced clinical stage and lymph node metastasis in COAD." (PMID 34781983, 2021). "A higher SRMS expression level was significantly associated with late TNM stages, more lymph node metastasis in COAD, but not with age, gender, race, histological." (PMID 34781983, 2021).
osteosarcoma (1 paper, 2021). A usually aggressive malignant bone-forming mesenchymal neoplasm, predominantly affecting adolescents and young adults. "We next generated SRMS knockout U2OS osteosarcoma cells via CRISPR/Cas9-mediated genome editing as an alternative methodology to RNA interference (RNAi)." (PMID 34077419, 2021).
ovarian carcinoma (1 paper, 2025). A malignant neoplasm originating from the surface ovarian epithelium. "In platinum treatment of ovarian cancer, ROS-activated SRMS deceases MKK4-JNK activation thereby contributing to resistance to platinum-based chemotherapy." (PMID 40001606, 2025).
Parkinson disease (1 paper, 2021). A progressive degenerative disorder of the central nervous system characterized by loss of dopamine producing neurons in the substantia nigra and the presence of Lewy bodies in the substantia nigra and locus coeruleus. "Analyses of SRMS mRNA expression and protein abundance have hinted that SRMS may serve as a biomarker for human diseases such as metastatic breast cancer and Parkinson’s disease." (PMID 34077419, 2021).
rectal tumors (1 paper, 2021). "We found that SRMS expression is broadly elevated in human breast, colon, and rectal tumors relative to corresponding normal tissues." (PMID 34077419, 2021).
rectum adenocarcinoma (1 paper, 2021). An adenocarcinoma arising from the rectum. "In rectum adenocarcinoma (READ) patients, SRMS expression was negatively correlated with nodal metastasis." (PMID 34781983, 2021).
triple-negative breast carcinoma (1 paper, 2021). An invasive breast carcinoma which is negative for expression of estrogen receptor (ER), progesterone receptor (PR), and human epidermal growth factor receptor 2 (HER2). "We next used the human triple-negative breast cancer cell line MDA-MB-231, which robustly expresses endogenous SRMS, to assess the effect of ibrutinib on the activity of endogenous SRMS." (PMID 34077419, 2021).
cancer (4 papers, 2020 to 2021). A tumor composed of atypical neoplastic, often pleomorphic cells that invade other tissues. "We illuminate SRMS overexpression as a previously unappreciated driver of aberrant PI3K-AKT signaling in human cancer and demonstrate that SRMS is a targetable vulnerability worth further investigation in diverse oncological settings." (PMID 34077419, 2021). "This illuminates SRMS as a targetable vulnerability in human cancers and as a new target for pharmacological induction of autophagy in vertebrates." (PMID 34077419, 2021). "In our prior work aimed at developing high-throughput methodologies for identifying mechanisms of action of bioactive natural products, we serendipitously identified SRMS as a negative regulator of autophagy in human cancer cells." (PMID 34077419, 2021). "SRMS is amplified and overexpressed in human cancers where it drives unrestrained AKT signaling in a kinase-dependent manner." (PMID 34077419, 2021). "Mechanistically, genetic or pharmacological inhibition of SRMS induced cancer cell senescence in an ATG5- and ATG7-dependent manner." (PMID 34077419, 2021). "We also present a structural model for the enzyme and discuss the potential involvement of SRMS in cancer cell signaling." (PMID 32545875, 2020). "In a recent proteomic study of serum samples from gastric cancer patients, SRMS was the only kinase found to be differentially expressed in cancer samples compared to normal controls." (PMID 32545875, 2020). "To investigate whether SRMS signaling contributes to cancer growth, we inactivated SRMS in human cancer cells and measured the effects on growth in culture and in vivo." (PMID 34077419, 2021). "Moreover, SRMS expression was correlated with many immune cells and immunostimulators, and these immune signatures were focused on inflammation and cancer signaling pathways." (PMID 34781983, 2021). "Additional studies are warranted in order to clarify the functions of SRMS and to determine whether SRMS and its signaling networks represent potential drug targets for cancer therapy." (PMID 32545875, 2020). "SRMS is expressed widely in normal mammalian tissue samples and in several cancer cell lines." (PMID 32545875, 2020). "It is also not yet known whether SRMS functions as a bona fide driver in cancer cells." (PMID 32545875, 2020).
tumor (3 papers, 2021). "Therefore, SRMS inhibits autophagy and accelerates tumor growth by direct phosphorylation of FKBP51." (PMID 34077419, 2021). "Therefore, it is biologically plausible that SRMS promotes tumor immunity by regulating multiple signaling pathways." (PMID 34781983, 2021). "Moreover, from the HPA database, protein expression levels of SRMS were high elevation in tumor tissues and moderate in normal tissues." (PMID 34781983, 2021). "Our work here nominates SRMS as a candidate gene that may help to explain why 20q copy number gains support tumor growth." (PMID 34077419, 2021). "Xenograft tumor growth was rescued in the SRMS knockout cells by reintroduction of wild-type SRMS but not the enzymatically inactive SRMS(K258A) mutant." (PMID 34077419, 2021). "Second, the mechanisms of SRMS-mediates tumor immunity were not fully evaluated." (PMID 34781983, 2021).
SRMS also shares sentences with these, for which no sentence is quoted: chromophobe renal cell carcinoma (1 paper); colon cancer (1); fibrosarcoma (1); lung adenocarcinoma (1); rectum cancer (1).